Y_RNA (Y RNA )
Gene: Miscellaneous RNA gene on chromosome 10 (124,814,958 to 124,815,062, reverse strand). Ensembl gene ENSG00000207494.
Homologues: Orthologues: chimpanzee Y_RNA (100% identical), macaque Y_RNA (79% identical). Paralogues in human: Y_RNA (88% identical), Y_RNA (87% identical), Y_RNA (86% identical), RNY1P5 (85% identical), Y_RNA (85% identical), Y_RNA (84% identical), Y_RNA (83% identical), Y_RNA (82% identical), RNY1P1 (81% identical), RNY1P6 (81% identical), Y_RNA (81% identical), RNY1 (80% identical), and 96 more.